CDKN2A (cyclin dependent kinase inhibitor 2A)
Diseases named in the same sentence as CDKN2A in open-access papers (continued):
Sharing a sentence is not in itself a finding about the gene and the disease.
cancer (continued). "Another recent study showed that somatic SVs enriched for enhancer hijacking also play a major role in shaping the cancer DNA methylome and regulating the expression of nearby genes, such as MYC, MYCN, TERT, ZFTA, KIAA1549, ATRX, and CDKN2A, in pediatric brain tumors." (PMID 40599851, 2025). "Importantly, we also showed that features of senescence including β-gal positivity, CDKN2A expression and proliferative rate in MSCs from MGUS and MM patients and from non-cancer controls strongly correlated with donor age." (PMID 40263435, 2025). "We conducted centralized re‐analysis of these genes in all index individuals by extracting data from targeted sequencing of a 360‐cancer gene panel and found no PVs in CDKN2A nor CDK4, confirming the previous routine testing results." (PMID 40072281, 2025). "CDKN2A, MTF1, LIAS, GLS, FDX1 and CDKN2A have been highlighted as the regulators of cuproptosis, with its expression correlating with poor survival outcomes in cancers." (PMID 41158129, 2025). "Finally, there is enough information on the role of CDKN2A, ZIC2, ELAVL2, and HS6ST2 genes in cancer." (PMID 40361484, 2025). "Some studies reported higher frequency of CDKN2A LoF in BE cases progressing to EAC compared to BEs that did not progress, implying that CDKN2A inactivation favors cancer initiation." (PMID 39753721, 2025). "Ten patients had germline mutations affecting cancer predisposition genes not typically linked to WT: CHEK2 in 4 children, and BLM, BRCA2, CDKN2A, FMN2, PIK3C3, and STK11 in one patient each." (PMID 40340749, 2025). "Only 15 matched lesions had either identical or clonally related CDKN2A alterations, confirming that CDKN2A LoF is not required for precancer to cancer transition." (PMID 39753721, 2025). "Thesame phenotype should be expected for most NSCLCs where the CDKN2A locus is absent(approximately 85% of such cancers)." (PMID 39906356, 2025). "Co-deletion of CDKN2A and MTAP due to its proximity occurs frequently across cancers." (PMID 40627883, 2025). "Our findings underscore the complexity of CDKN2A regulation in cancer and demonstrate that neither promoter nor exon 2 methylation alone is predictive of gene expression." (PMID 40649906, 2025). "Despite several reports of a lower infiltration of immune cells in cancers with reduced CDKN2A expression, CDKN2A LoF alone does not change the immune composition of BE or EAC TME." (PMID 39753721, 2025). "Next, CDKN2A DEL was not related to OS in either primary or metastasis cancers (HR, 1.23; 95% CI, 0.55–2.77; metastasis, HR, 1.20; 95% CI, 0.38–3.74)." (PMID 38822443, 2024). "Due to the fact that CDKN2B is almost always deleted together with CDKN2A in human cancer, it has not received sufficient scientific interest." (PMID 38561743, 2024). "The status of CDKN2A/B was further confirmed with cancer genome profiling (CGP) test in 12 cases (7 cases were analyzed with FoundationOne®CDx and 5 cases were analyzed with OncomineTM Childhood Cancer Research Assay)." (PMID 39117984, 2024). "Or the absence of SL vulnerability in cancer with CDKN2A wild type, 9p21 intact presents a situation of limited cytotoxicity from pemetrexed for malignant tissue, thus making the therapeutic index close to zero." (PMID 38187871, 2024). "Subsequent genomic profiling, utilizing DNA-based cancer panel sequencing (Oncomine Comprehensive Assay Plus), revealed a homozygous deletion of the CDKN2A and MTAP gene locus but did not identify further actionable mutations." (PMID 39085487, 2024).
cancer (continued). "The tumour suppressor p16/CDKN2A and the metabolic gene, methyl-thio-adenosine phosphorylase (MTAP), are frequently co-deleted in some of the most aggressive and currently untreatable cancers." (PMID 38755480, 2024). "There is no clear consensus on the recommendations for surveillance in CDKN2A GPV carriers, although the latest guidelines from the International Cancer of the Pancreas Screening Consortium recommend annual endoscopic ultrasound (EUS) or magnetic resonance imaging (MRI) regardless of family history." (PMID 36980574, 2023). "The correlation calculated for all paired samples (33 cancer types) revealed that of the 10 cuprotosis molecules, six (DLAT, DLD, MTF1, CDKN2A, GLS and FDX1) may be negatively regulated by many miRNAs." (PMID 36895378, 2023). "To investigate the biological functions of CDKN2A in LGG, in which cancer type the CDKN2A could predict the prognosis, we firstly detected the expression of p16 in clinical LGG samples and designed siRNAs to target the CDKN2A expression." (PMID 36961395, 2023). "Given that STK11/LKB1, CDKN2A, and PTK6 each have well-described roles in cancer progression, we hypothesized that PAQR8 might play a role in breast cancer recurrence." (PMID 36597146, 2023). "Additionally, the CNV condition and expression level of ASF1A, CDKN2A, MAGOHB, NADK, SPOP, and ARC were remarkably correlated in most cancer types." (PMID 37497116, 2023). "This suggests that CDKN2A and CDKN2B play an important role in certain cancer types." (PMID 35253368, 2022). "The following most altered cancer genes were LRP1B (26%), PIK3CA (24%), CDKN2A (24%), PTPRD (15%), RB1 (13%), PDE4DIP (13%), PCLO (11%), KRAS (11%), FAT1 (10%), and RELN (10%), and these results partially overlap with the most altered genes depicted in the experimental cohort." (PMID 35330454, 2022). "CDKN2A expression was significantly higher among patients with T2-stage HNSCC than among patients with T3-and T4-stage HNSCC, indicating that CDKN2A expression is high in early malignant tumours and low in advanced malignant tumours." (PMID 36699463, 2022). "patients with high expression of CDKN2A, MTF1, and GLS had worse prognoses, suggesting that CDKN2A, MTF1, and GLS might promote the proliferation of cancer cells." (PMID 36159561, 2022). "As reintroduction of CDKN2A into cancer cells lacking CDKN2A delays cell cycle progression, we determined the percent of variant-expressing PANC-1 cells in G1, G2/M, and S phases of the cell cycle." (PMID 35001868, 2022). "Interestingly, most of these common candidates are large cancer genes within fragile sites, such as FHIT, WWOX, CCSER1, IMMP2L, CDKN2A, and CDKN2B26,44–47." (PMID 36163358, 2022). "In conclusion, CRGs, especially CDKN2A, may serve as potential prognostic predictors in HCC patients and provide novel insights into cancer therapy." (PMID 36588699, 2022). "Other tumor suppressor genes, such as cyclin-dependent kinase inhibitor 2A (CDKN2A), retinoblastoma (Rb), Von Hippel–Lindau (VHL), and breast cancer 1 (BRCA1) have also been identified in the cancer cells as being inactivated via an ROS-dependent epigenetic modulation." (PMID 36293510, 2022). "MTAP gene is often found deleted in various cancer types and not necessarily co‐deleted with CDKN2A." (PMID 35766227, 2022). "In addition, we found that high expression of most of these genes predicted poor prognosis in cancer patients, such as FDX1 in LUAD and LGG; LITP1 in SKCM and UVM; DLAT in BLCA and LIHC; and CDKN2A in KICH, ACC, THCA, LIHC, LIHC, KIRC UCEC and COAD." (PMID 36581992, 2022).
cancer (continued). "Hence, once removed from cancer cells, IL6, IL8, VEGF, CDKN2A and LMNB1 mRNA levels in MSCs return to levels observed in MSCs without cancer cells." (PMID 36358839, 2022). "A meta-analysis across six different cancer types highlights the potential pan-cancer relevance of CDKN2A deletion as a negative indicator of clinical benefit after immunotherapy." (PMID 35739333, 2022). "Compared to Del-c1 and c3, the majority of cancer genes were deleted by DEL-c2, such as CDKN2A (207/528), FHIT (133/528), KDM6A (42/528), RB1 (27/528), FAT1 (23/528), NFE2L2 (13/528), ERBB4 (20/528), CUL3 (11/528), PTEN (9/528), ZNF750 (13/528) and NOTCH1 (8/528)." (PMID 36272974, 2022). "Furthermore, we compared the differential expressions of cuproptosis-related genes between OSCC tissues and para-cancer tissues and found that four genes (LIAS, PDHB, GLS, and CDKN2A) were differentially expressed." (PMID 35875097, 2022). "The genomic features that are linked to the responses of the two drugs are also biologically relevant; for example, EGFR is the upstream factor of PI3Ks, and the effectiveness of combined CDK4/6 (targets of CDKN2A) and PI3K inhibition has been shown in other cancer models." (PMID 35992090, 2022). "The expression of CDKN2A, CDKN2B, CDKN2C, and CDKN2D was analyzed in 20 types of cancers." (PMID 35771229, 2022). "According to the data, numerous genes (such as H2AFX, CDKN2A, TTF2, IKBKE, and UBE2I) were markedly upregulated in many cancer types, while some genes (such as ARRB1, LMO3, KHDRBS2, CIRBP, and RALYL) were remarkably downregulated in multiple cancer types." (PMID 35003212, 2021). "Due to its role as cell cycle brake, it is not surprising that ~50% of human cancer shows decreased expression of CDKN2A." (PMID 33918220, 2021). "CDKN2A and MTAP were ~100 kb apart on 9p21.3 and commonly co-deleted in human cancers." (PMID 34556668, 2021). "To confirm the PARIS predictions and test the sensitivity of cancer cells to TYMS inhibition, we treated a panel of cell lines with different CDKN2A genetic backgrounds with increasing doses of PMX (ranging from 10 nM to 15 μM) and measured cell viability as a readout for synthetic lethality." (PMID 34454516, 2021). "For this reason, we focused on four MYC-interacting proteins, i.e., Promyelocytic leukemia protein (PML), Glycogen synthase kinase-3 beta (GSK3B), Cyclin-Dependent Kinase Inhibitor 2A (CDKN2A), and Histone deacetylase 2 (HDAC2), which were reported to be mis-regulated in cancer in previous studies." (PMID 36303724, 2021). "MYC, CDKN2A, PTEN, HARS, APC2, and APC are often referred to as miRNAs in cancer." (PMID 33959508, 2021). "In addition to homozygous deletion (HD), loss of heterozygosity (9p21 LOH) due to hemizygous deletion of CDKN2A and MTAP was observed in 24.6% and 27.8% of cancers, respectively." (PMID 34556668, 2021). "CDKN2A (p16), used as a key biomarker for HPV status, exhibited the most extensive hyper-5hmC in HPV(+) tumors, while HPV(−) tumors showed hyper-5hmC in CDH13, TIMP2, MMP2 and other cancer-related genes." (PMID 33203436, 2020).
cancer (continued). "As expected, all cancers with bi-allelic (homozygous) CDKN2A deletion completely lacked p16 expression, which indirectly validates our experimental approaches both for FISH and IHC." (PMID 32256975, 2020). "Some TSGs, including GSTP1, MGMT, CDH1, P16, RAR-β2, septin 9 (SEPT9), syndecan 2 (SDC2), cyclin-dependent kinase inhibitor 2A (CDKN2A), and short stature homeobox 2 (SHOX2), have been validated to be silenced through DNA methylation in various types of cancer." (PMID 32075099, 2020). "Considering that the MTAP gene is frequently codeleted with the adjacent cyclin‐dependent kinase inhibitor 2A (CDKN2A) locus in MM, we assessed whether PRMT5 could represent a therapeutic target also for this cancer type." (PMID 32301278, 2020). "Since MTAP is frequently deleted in human cancers due to its chromosomal proximity to CDKN2A, it was also speculated that inhibitors of PRMT5 could be utilized in potential therapy for MTAP/CDKN2A‐deleted tumors." (PMID 33155773, 2020). "Notably, the expression of the MIZ1 target genes Cdkn1a, Cdkn2a, and Cdkn2b, known to be repressed by MYC–MIZ1 complexes in cancer cells, were also similar between the LZ of MycVD and MycWT." (PMID 32407433, 2020). "Furthermore, the list of typically early drivers includes most other highly recurrent cancer genes, such as KRAS, TERT and CDKN2A, indicating a preferred role in early and possibly even pre-cancer evolution." (PMID 32025013, 2020). "In addition, we found two relatively common cancer genes in more than one rare cancer case: ARID1A (occurred in two cases and twice in one case) and CDKN2A (occurred in two cases)." (PMID 32570879, 2020). "It is also worth noting that some cell cycle regulators, such as CDKN2A, are inactivated in cancer cells by deletion of the entire gene rather than by point mutations." (PMID 31454903, 2019). "With regards to known cancer drivers, 24 showed alterations, including the oral cell lineage transcription factors TP63 (amplified, 21.94%) and SOX2 (amplified, 20.97%), CDKN2A, CCND1 (amplified, 24.27%), PIK3CA (amplified, 20.97%) and EGFR (amplified, 10.67%)." (PMID 31703248, 2019). "In the absence of CDKN2A, a common driver event in human cancers, the control of the G1/S cell cycle checkpoint is impaired." (PMID 30655555, 2019). "In summary, except for CDKN2A, which is a clear outlier in the dataset under consideration, the changes in the local number of CNVs did not appear to be connected to the pan-cancer genes located in these regions (CAMTA1 and MTOR, MUC4 and TFRC, and NCOR2)." (PMID 31783642, 2019). "Since CDKN2A/B locus genes are known for their roles in cell cycle regulation and cancer, and not metabolism, many questions remain as to how this locus impacts metabolic disease." (PMID 30087655, 2018). "Furthermore, using cancer patients’ cell-free DNA, we develop PCR-based EBV copy and CNV tests (CCND1 and CDKN2A) to provide drug guidance information." (PMID 30236142, 2018).
cancer (continued). "Mutual exclusivity analysis with genomic alteration data showed that STK11 alterations in cancer patients rarely co-occur with CDK4, CDKN2A, CDKN2B or RB1, supporting a role for STK11 in an oncogenic pathway that is intimately associated with cell cycle function." (PMID 28205554, 2017). "As both CDKN2C and RB1 interact with G1/S cell cycle checkpoint through CDK4/6, they are potentially targetable through CDK4/6 inhibition, for which it has been shown in other cancers that co-deletion of CDKN2C and CDKN2A with functional presence of RB1 increases sensitivity in cell lines." (PMID 28427158, 2017). "Another reason why the CDKN2A and BRCA families behaved differently may be that all the probands in the current study had, by definition, survived their cancers." (PMID 27804060, 2017). "Cyclin dependent kinase inhibitor 2A (CDKN2A) encodes p16INK4A, an Rb pathway gene which is nearly ubiquitously expressed in HPV-positive cancers due to activation of a negative feedback loop triggered by E2F release." (PMID 28771191, 2017). "We examined the DNA methylation levels of SFRP1, SFRP2, SFRP5, DKK2, DKK3, mir34b/c, RASSF1A, IGFBP7, CDKN2A, and MLH1 in normal colonic crypts isolated from regions that were adjacent to the cancer, as well as distal and proximal regions (left and right sides)." (PMID 28533824, 2017). "Furthermore, four key genes highly involved in ‘pathways in cancer,’ BIRC5, E2F1, CCNE1 and CDKN2A, were bioinformatically validated and selected out for further diagnostic and prognostic tests." (PMID 28316892, 2017). "In contrast to the TCGA-data, the ‘top 20’ list of ‘Cancer census genes’ most frequently involved in a copy number loss in the LP-WGS-data did not contain NF2, CDKN2A or BAP1." (PMID 29371938, 2017). "These segments contain known cancer genes including MYC, EGFR, ERBB2 CDKN2A, RB1 and STK11." (PMID 28686671, 2017). "For example, known disease genes BRCA2, CDH1, IDH1, CDKN2A, NME1 and FGFR3 frequently occurred at the top one in seven cancer types (including BC, GC, GBM, MB, MM, NB and OC), even though only two or three known-disease genes existed in NB, GBM and MB gene lists." (PMID 28076842, 2017). "It is also noteworthy that UHRF1 regulates a plethora of other TSGs among which RB1 especially in Jurkat and osteosarcoma cells, CDX2, CDKN2A, RUNX3, FOXO4, PPARG, BRCA1 and PLM, in gastric cancer, SOCS3 and 3OST2 in endometrial carcinoma as well as BRCA1 in cancer breast cell lines." (PMID 27839516, 2016). "Of note, the CCND1 and CDKN2A loci show some of the highest frequencies of amplification and deletion rates seen in SCCHN and several other cancer types; this further supports the idea that it may be important to restrain RB1 function post-translationally." (PMID 26265441, 2015).